KIT (KIT proto-oncogene, receptor tyrosine kinase)
Diseases named in the same sentence as KIT in open-access papers (continued):
Sharing a sentence is not in itself a finding about the gene and the disease.
gastrointestinal stromal tumor (continued). "Our purpose is to define the distribution of c-KIT, PDGFR and BRAF mutations in a population-based cohort of gastrointestinal stromal tumors (GIST) patients and correlate them with anatomical site, risk classification and survival." (PMID 25885906, 2015). "c-KIT is one of the primary targets of imatinib, and mutations in KIT are predictive of the efficacy of the drug in gastrointestinal stromal tumors (GIST)." (PMID 26572169, 2015). "Due to these other activities, imatinib is effective at treating gastrointestinal stromal tumors (GIST) which are dependent on c-KIT, many other cancers, and steroid refractory Graft-versus-Host disease which requires PDGFRA activity." (PMID 25685324, 2014). "Gastrointestinal stromal tumor (GIST) is the most common GI mesenchymal neoplasm and nearly all GIST express KIT (CD117)." (PMID 23433424, 2013). "The non-recurrent translocation group tends to show complex genomic changes including gains/amplifications and deletions in multiple chromosomal regions, or activating mutations (e.g. KIT and PDGFRA) in gastrointestinal stromal tumors (GIST)." (PMID 23217126, 2012). "KIT mutations are frequently found in gastrointestinal stromal tumors (GIST) and have been shown to be highly sensitive to imatinib, a tyrosine kinase inhibitor (TKI) targeting ABL, PDGF-R, and KIT, thus providing a potential for targeted therapy in patients with KIT mutations in melanoma." (PMID 22333219, 2012). "The KIT-inhibitor imatinib mesylate (IM) has greatly improved the treatment of metastatic gastrointestinal stromal tumors (GIST)." (PMID 22662219, 2012). "For example, KIT in gastrointestinal stromal tumor (GIST; second highest weight in GIST, 0.95) and KLK2 and KLK3 in prostate cancer (the two highest weights in prostate adenocarcinoma, 0.97 and 0.95, respectively)." (PMID 21955394, 2011). "They include imatinib mesylate (or “Gleevec”/“Glivec”) for BCR-ABL inhibition in Chronic Myeloid Leukemia (CML) and for KIT inhibition in gastrointestinal stromal tumors (GIST), respectively." (PMID 21379385, 2011). "Sunitinib’s initial clinical development in the early 2000s focused on metastatic renal cell carcinoma (mRCC) and gastrointestinal stromal tumors (GIST), two tumor types highly dependent on VEGF-, PDGF-, and KIT-mediated pathways." (PMID 41517566, 2026). "Neurofibromatosis type 1 (NF1)-associated gastrointestinal stromal tumor (GIST) is a distinct subtype of wild-type GIST driven by loss of neurofibromin function rather than KIT or PDGFRA mutations." (PMID 42176217, 2026). "The tyrosine kinase inhibitor (TKI) imatinib targets KIT and PDGFRA, offering significant therapeutic benefits in advanced gastrointestinal stromal tumors (GISTs)." (PMID 40921853, 2025). "In recent years, various inhibitors of KIT have been developed, with several gaining FDA approval for gastrointestinal stromal tumor (GIST)." (PMID 39959669, 2025). "Imatinib is the standard first-line systemic treatment for chronic myeloid leukemia and Gastrointestinal Stromal Tumor (GIST), targeting BCR-ABL and c-KIT tyrosine kinases, respectively." (PMID 39112280, 2024). "For instance, sequencing of receptor tyrosine kinases (RTKs) like KIT and PDGFRA in gastrointestinal stromal tumors (GISTs) can guide the use of targeted therapies like imatinib." (PMID 38228904, 2024). "Gastrointestinal stromal tumors (GISTs) arise from the mesodermal interstitial cells of Cajal (ICC), which are characterized by the expression of the c-KIT protein." (PMID 39376980, 2024). "EGFR, KIT, and FLT3 mutants are well known as major oncogenic drivers of lung adenocarcinoma (LAD), gastrointestinal stromal tumor (GIST)/mast cell leukemia (MCL), and acute myeloid leukemia (AML), respectively." (PMID 38679330, 2024).
gastrointestinal stromal tumor (continued). "KIT (proto-oncogene tyrosine-protein kinase) is a transmembrane receptor for mast cell growth factor and found to be constitutively active in 75% of gastrointestinal stromal tumors (GIST)." (PMID 39507544, 2024). "Imatinib, a specific tyrosine kinase inhibitor that targets the BCR‐ABL, KIT and PDGFR receptors, is used to treat various cancers, including but not limited to chronic myeloid leukaemia and gastrointestinal stromal tumours." (PMID 37909856, 2023). "Gastrointestinal stromal tumors (GIST) are tyrosine kinase receptor (KIT)-expressing and KIT-signaling driven mesenchymal tumors." (PMID 38024086, 2023). "For the treatment of gastrointestinal stromal tumours (GISTs), the FDA approved the targeted drug Imatinib, a TKI that inhibits both c-KIT and PDGFR." (PMID 37681936, 2023). "Resistance to the approved inhibitors of KIT proto-oncogene, receptor tyrosine kinase (KIT), and platelet-derived growth factor receptor α (PDGFRA) is a serious clinical challenge for patients with advanced gastrointestinal stromal tumors." (PMID 37046734, 2023). "For example, among the top three exclusively mutated gene pairs are BRAF and NRAS in skin cutaneous melanoma (p = 1.1 × 10–44), KIT and PDGFRA in gastrointestinal stromal tumour (p = 3.3 × 10–37), and EGFR and KRAS in lung adenocarcinoma (p = 6.6 × 10–29)." (PMID 37550388, 2023). "This study aims to evaluate whether CT based sarcopenia could differentiate KIT/PDGFRA wild-type gastrointestinal stromal tumor (wt-GIST) from the mutant-type GIST (mu-GIST), and to evaluate genetic features of GIST." (PMID 36828845, 2023). "Hence, researchers tested a drug conjugate, SCF-DM1, in gastrointestinal stromal tumor (GIST) cells, revealing inhibitory effect on KIT signaling." (PMID 38313431, 2023). "Imatinib mesylate is a tyrosine kinase inhibitor that targets the BCR-ABL protein, c-KIT, and platelet-derived growth factor (PDGF) receptors and is used to treat CML, gastrointestinal stromal tumors, and dermato-fibrosarcoma protuberant." (PMID 37323347, 2023). "Mutations in KIT proto-oncogene, receptor tyrosine kinase (KIT) and platelet-derived growth factor receptor-α (PDGFRA) render the available tyrosine kinase inhibitors (TKI) ineffective in treating advanced gastrointestinal stromal tumors (GIST)." (PMID 37274264, 2023). "c-KIT is a promising therapeutic target against gastrointestinal stromal tumor (GIST)." (PMID 36612139, 2022). "Gastrointestinal stromal tumors (GISTs) are common ICC precursor sarcomas, which are considered to be a potential malignant mesenchymal tumor driven by specific KIT or PDGFRA signals in the gastrointestinal tract." (PMID 35646090, 2022). "Wild-type KIT and PDGFRA gastrointestinal stromal tumors (GIST) are rare tumors with limited treatment options." (PMID 35388076, 2022). "Additionally, miR-494 suppresses gastrointestinal stromal tumor (GIST) cell proliferation via targeting KIT, a critical regulatory protein in the development and progression of GIST." (PMID 35668527, 2022). "At the same time, researchers firstly attempted to use imatinib mesylate, a selective tyrosine kinase inhibitor (TKI) of c-KIT and platelet-derived growth factor receptors, for patients with chordoma as it was shown to be highly effective in gastrointestinal stromal tumors (GIST)." (PMID 36465398, 2022). "A previous study showed that silencing the adaptor molecule SH3 Binding Protein 2 (SH3BP2) reduced oncogenic KIT and PDGFRA receptor levels and impaired gastrointestinal stromal tumor (GIST) growth." (PMID 36551682, 2022). "This makes KIT an attractive target for NB therapy, since several drugs, which can target KIT are used for chronic myeloid leukemia (CML), gastrointestinal stromal tumors (GIST) and kidney cancers." (PMID 35887076, 2022).
gastrointestinal stromal tumor (continued). "Gastrointestinal stromal tumors (GIST) are the most common mesenchymal tumors of the digestive tract, and are mainly driven by activating mutations in KIT (also known as CD117) or platelet-derived growth factor A (PDGFRA), accounting for 0.1–3% of all gastrointestinal tumors." (PMID 34805171, 2021). "Molecular analysis of KIT and PDGFRA is critical for tyrosine kinase inhibitor treatment selection of gastrointestinal stromal tumors (GISTs) and hence recommended by international guidelines." (PMID 33909171, 2021). "Gastrointestinal stromal tumors (GIST) are mesenchymal tumors mostly attributable to genetic or epigenetic alterations, as KIT and PDGFRα receptors, tyrosine kinase, and SDH subunit mutations." (PMID 34201149, 2021). "c-KIT is a type III transmembrane receptor tyrosine kinase (RTK) found on the surface of cells in many cancer types, including gastrointestinal stromal tumors (GIST), systemic mastocytosis, and subsets of acute myeloid leukemia and melanoma." (PMID 33807778, 2021). "Whereas targeted therapy against c-KIT has been effective in treating gastrointestinal stromal tumors (GIST), its inhibitory activity is far less impressive in c-KIT-mutant melanoma, and responses tend to be short lived, with a median time to progression of three months." (PMID 32517051, 2020). "Sunitinib (a second-line chemotherapeutic agent that inhibits multiple kinases, including KIT and PDGFR) is widely used in imatinib-resistant patients with gastrointestinal stromal tumors (GISTs)." (PMID 30224936, 2018). "Gastrointestinal stromal tumors (GIST) that lack KIT or platelet-derived growth factor receptor alpha (PDGFRA) mutations, that are around 10–15% of all cases, have always been classified as KIT/PDGFRA wild type GIST, short-named WT GIST." (PMID 28535771, 2017). "For example, Sorafenib, a VEGFR, PDGFR, KIT, FLT3, and RAF inhibitor, was recently evaluated in clinical trials for its effectiveness against gastrointestinal stromal tumors." (PMID 29132432, 2017). "Gastrointestinal stromal tumor (GIST), the most major mesenchymal neoplasm of the digestive tract, is characterized by KIT or platelet-derived growth factor receptor alpha (PDGFRA) activating mutations, which approximately account for 80% or 10% of GISTs respectively." (PMID 27506146, 2016). "Gastrointestinal stromal tumors (GIST) exhibit a strong oncogenic dependency on KIT and KIT inhibitors confer long lasting disease stabilization in the majority of patients." (PMID 27167336, 2016). "Several small studies indicated that the genotype of KIT or platelet-derived growth factor receptor-α (PDGFRA) contributes in part to the level of clinical effectiveness of sunitinib in gastrointestinal stromal tumor (GIST) patients." (PMID 26772734, 2016). "Although treatment with imatinib, which inhibits KIT and PDGFR, controls advanced disease in about 80% of gastrointestinal stromal tumor (GIST) patients, resistance to imatinib often develops." (PMID 26893362, 2016). "Gastrointestinal stromal tumors (GIST) comprise the most common primary mesenchymal malignancies of the gastrointestinal tract, and approximately 95 % of these tumors express the cell-surface transmembrane receptor KIT that has tyrosine kinase activity." (PMID 26772734, 2016). "Several patients had multiple aberrations; a patient with wild-type gastrointestinal stromal tumor harbored five alterations (MDM4, MCL1, KIT, AKT3, and PDGRFA)." (PMID 26328274, 2015). "Additionally, the discovery and treatment of the targetable alterations in hot spot regions in the KIT or PDGFRA genes in gastrointestinal stromal tumors (GIST) has significantly improved overall survival of these patients." (PMID 26415226, 2015).
gastrointestinal stromal tumor (continued). "The best example for molecular targeted therapy in mesenchymal tumors is treatment with tyrosine kinase inhibitors in gastrointestinal stromal tumors (GIST) which carry activating KIT or PDGFRA (platelet derived growth factor receptor alpha) mutations in approximately 90%." (PMID 25844809, 2015). "Our previous study demonstrated NVP-AUY922, a HSP90AA1 inhibitor, could enhance mutant KIT degradation in gastrointestinal stromal tumor (GIST) cells through both proteasome- and autophagy-mediated pathways." (PMID 25375091, 2014). "Deletions in the juxtamembrane domain of both KIT and PDGFR have been identified in human gastrointestinal stromal tumors." (PMID 24739671, 2014). "Gleevec® also inhibits another kinase called c-KIT, which has enabled its use for patients who are diagnosed with KIT-positive gastrointestinal stromal tumours." (PMID 23885284, 2013). "As an illustration, the efficiency of GleevecTM to treat chronic myelogenous leukemia (CML) and gastrointestinal stromal tumors (GIST) is a consequence of its capacity to bind to and stabilize the inactive form of KIT and its binding preferences are governed by conformational selection." (PMID 21698178, 2011). "Nilotinib is currently being investigated for repurposing to determine its potential therapeutic benefits in other conditions, particularly in tumours with KIT or PDGFR alterations, including gastrointestinal stromal tumours (GIST) and melanoma, where early studies have shown encouraging results." (PMID 41155542, 2025). "Currently, there are few studies investigating the molecular expression of KITLG and c-KIT in veterinary medicine, mostly in canine mast cell tumors and gastrointestinal stromal tumors, with no descriptions of specific immunolabeling in canine SCC or DSCC." (PMID 36851392, 2023). "DOG1 is expressed in ~99% of gastrointestinal stromal tumors (GISTs) derived from Cajal cells regardless of conventional KIT (CD117) or platelet derived growth factor receptor alpha (PDGFRA) mutation status." (PMID 36776873, 2023). "Gastrointestinal stromal tumors (GISTs) are the most common mesenchymal tumors of the canine gastrointestinal tract and are diagnosed by the immunohistochemical expression of the receptor tyrosine kinase (RTK) KIT." (PMID 35878393, 2022). "Gastrointestinal stromal tumor (GIST) is defined as a stromal tumor of spindle or epithelioid cells that is primary in the gastrointestinal tract, greater omentum, and mesentery with a KIT (CD117 stem cell factor receptor) positive stain." (PMID 34558731, 2021). "Gastrointestinal stromal tumor (GIST) initiation and evolution is commonly framed by KIT/PDGFRA oncogenic activation, and in later stages by the polyclonal expansion of resistant subpopulations harboring KIT secondary mutations after the onset of imatinib resistance." (PMID 32024476, 2020). "A gastrointestinal stromal tumor (GIST) is defined as a spindle, epithelioid, or occasionally pleiomorphic mesenchymal tumor of the gastrointestinal tract that expresses the KIT protein, and approximately 2% of all neoplasms of the gastrointestinal tract are classified as GISTs." (PMID 31590135, 2019). "Later on, the indolinone-derivative sunitinib with a broad spectrum activity targeting VEGFR, PDGFR, FGFR, KIT, and FLT3, was approved for the treatment of renal cell carcinoma, as well as second-line therapy in the imatinib-resistant gastrointestinal stromal tumor (GIST)." (PMID 29455673, 2018).
gastrointestinal stromal tumor (continued). "This phenomenon is for instance well known in the subset of gastro-intestinal stromal tumors that are wild-type for the KIT and PDGFRA genes and generally do not respond to TKIs such as Imatinib and Sunitinib." (PMID 27741505, 2017). "Also, it has been reported that HSP90β and Apaf-1 have a high binding affinity in AML cells and gastrointestinal stromal tumor (GIST) cells, which are c-KIT-positive cells." (PMID 29127384, 2017). "We report the identification of clinically relevant and previously unreported genomic alterations in gastrointestinal stromal tumors (GISTs) lacking genomic alterations in KIT, PDGFRA, SDH, and the RAS pathway." (PMID 27974047, 2016). "Mutations in c-KIT result in SCF-independent activation of downstream signaling pathways associated with increased proliferation and cell survival, mostly found in leukemia, gastrointestinal stromal tumors (GIST), testicular germ cell tumor (TGCT) and melanoma." (PMID 26404379, 2015). "Recently a few cases of synovial sarcoma (SS) of the abdominal viscera have been reported, raising awareness about the potential for confusion between this entity and KIT-negative gastrointestinal stromal tumors (GIST)." (PMID 25699170, 2015). "Unlike the situation for gastrointestinal stromal tumors (GIST), activating mutations in the KIT gene were minimally associated with the immunohistochemical expression of c-Kit in HGNEC." (PMID 25989941, 2015). "Gastrointestinal stromal tumors (GISTs) represent the majority of primary non-epithelial neoplasms of the digestive tract, most frequently expressing the KIT protein detected by immunohistochemical staining for the CD117 antigen." (PMID 25170380, 2014). "Advanced gastrointestinal stromal tumors (GIST), a KIT oncogene-driven tumor, on imatinib mesylate (IM) treatment may develop secondary KIT mutations to confer IM-resistant phenotype." (PMID 23840364, 2013). "For chronic myelogenous leukaemia or gastrointestinal stromal tumours (GIST), imatinib (Gleevec), a tyrosine kinase inhibitor that targets platelet-derived growth factor receptor, KIT, and the BCR-ABL oncoprotein, is remarkably effective in providing long-term control." (PMID 21556173, 2011). "Imatinib mesylate (STI571, Gleevec) is a selective inhibitor of the tyrosine kinases BCR-ABL, c-KIT and PDGF-R and has been shown to be highly active in chronic myeloid leukemia (CML) and has significant antitumor efficacy against gastrointestinal stroma tumors (GIST)." (PMID 18781906, 2008). "Imatinib (Glivec®, formerly STI571), in the US imatinib mesylate (GleevecTM), the selective inhibitor of KIT BCR-ABL and PDGFR tyrosine kinases, is the only effective and approved systemic therapy for the treatment of patients with advanced gastrointestinal stromal tumours (GISTs)." (PMID 14562006, 2003). "In gastrointestinal tract cancers, NTRK fusions are relatively highly detected in gastrointestinal stromal tumor (GIST), primarily in cases without KIT, PDGFRA, or RAS mutations, and in colorectal cancer, most frequently in Microsatellite Instability (MSI)-high tumors." (PMID 41516212, 2025). "Regorafenib is an oral multikinase inhibitor targeting VEGFR1–3, c-KIT, RAF, and FGFR, which inhibits tumor angiogenesis and significantly delays tumor growth, and has been approved for treating metastatic colorectal cancer, advanced gastrointestinal stromal tumors, and hepatocellular carcinoma." (PMID 41395622, 2025). "Ripretinib, a broad‐spectrum inhibitor of the KIT and PDGFRA receptor tyrosine kinases, is designated as a fourth‐line treatment for gastrointestinal stromal tumor (GIST)." (PMID 38973363, 2024). "Imatinib, a tyrosine kinase inhibitor (TKI) that targets ABL, BCR-ABL, PDGFRA, and c-KIT, is widely used in treating chronic myelogenous leukemia (CML) and gastrointestinal stromal tumors (GIST)." (PMID 39589949, 2024). "A KIT-negative gastrointestinal stromal tumor was suspected based on the biopsy findings." (PMID 37902858, 2023).